RNU6-623P (RNA, U6 small nuclear 623, pseudogene)
Gene: Small nuclear RNA gene on chromosome 17 (60,662,333 to 60,662,437, reverse strand). Ensembl gene ENSG00000200013.
Homologues: Orthologues: macaque U6 (96% identical), pig U6 (85% identical), mouse Gm55140 (72% identical), guinea pig U6 (67% identical), mouse Gm55125 (67% identical), rat LOC120093923 (64% identical), mouse Gm56276 (63% identical). Paralogues in human: RNU6-1011P (91% identical), RNU6-949P (91% identical), RNU6-1060P (90% identical), RNU6-116P (90% identical), RNU6-19P (90% identical), RNU6-24P (90% identical), RNU6-1175P (90% identical), RNU6-11P (90% identical), RNU6-12P (90% identical), RNU6-13P (90% identical), RNU6-26P (90% identical), RNU6-31P (90% identical), and 1286 more.